UBE3A (ubiquitin protein ligase E3A)
Diseases named in the same sentence as UBE3A in open-access papers (continued):
Sharing a sentence is not in itself a finding about the gene and the disease.
autism (continued). "These enrichment results support the translational relevance for human patients with autism or dup15q syndrome of the sex-specific transcriptomic dysregulation produced by increased dosage of Ube3a." (PMID 38996019, 2024). "Although molecular and cellular analyses shaped a putative mechanism, a concrete linkage between UBE3A and autism is yet to be revealed." (PMID 39202440, 2024). "In the context of Dup15q syndrome, additional genomic copies of UBE3A give rise to the autism, muscle hypotonia and spontaneous seizures characteristics of the disorder." (PMID 39197537, 2024). "This paves new avenues for modifying upstream regulators of UBE3A to ameliorate clinical manifestations of autism." (PMID 38248358, 2023). "Aggression is increased due to increases of Ube3a gene dosage in the VMHvl neurons when modeling autism due to maternal 15q11-13 triplication." (PMID 36909588, 2023). "These experimental results hinted towards the existence of novel molecular mechanisms underlying UBE3A and SNORD116 expression in PBMCs and brain-related processes associated with motor and language impairments and autism-like features in these disorders." (PMID 38248358, 2023). "The reported findings suggested the presence of novel interactions between expression of UBE3A and SNORD116, with brain specific processes underlying motor and language impairments in autism and these chromosome 15 imprinted genetic disorders." (PMID 36980949, 2023). "Conversely, light enhances the activity when mice are in the light, and the circadian period of the cultured SCN clock in vitro is shorter when Ube3a is over-expressed in an autism mouse model." (PMID 35401134, 2022). "The findings suggest presence of novel interactions between expression of UBE3A and SNORD116 in PBMCs and brain specific processes underlying motor and language impairments and autism features in these disorders." (PMID 33116122, 2020). "One of the first studies that examined the cellular functions of UBE3A showed that in dup15q autism, where UBE3A is overexpressed, there is a mitochondrial dysfunction." (PMID 32532103, 2020). "Previous studies identified that UBE3A gene was an important candidate gene of autism, but there are few studies about the relationship between this gene and ASD in Chinese Han population." (PMID 33308194, 2020). "Specifically, increased UBE3A mRNA levels correlated with increased autism features in PWS and receptive language skills in AS, suggesting the utility of gene expression analysis in peripheral tissues as non-invasive biomarkers for future studies." (PMID 33116122, 2020). "Loss of function of Ube3A/E6AP results in the manifestation of AS, whereas duplication and triplication of the gene cause autism, suggesting the sensitivity of neurodevelopmental processes to the E6AP dosage." (PMID 31114479, 2019). "Here, we study axon and dendrite contact guidance and neuronal morphological features of wild-type, AS, and UBE3A-overexpressing neurons (Dup15q autism model) on micrograting substrates, with the aim to clarify the role of UBE3A in neuronal guidance." (PMID 31798818, 2019). "In fact, most of the AS phenotypes (i.e., epilepsy, autism- and anxiety-related features) appear to be established early and are only rescued when Ube3a is reinstated during prenatal or early postnatal development." (PMID 31798818, 2019). "Because of the link of UBE3A with AS and autism, researcher becomes increasingly interested to understand the regulation of synaptic function and plasticity by UBE3A." (PMID 30568575, 2018). "Fly models overexpressing Ube3a have been shown to display comparable neurotransmission defects to those found in mouse models of duplication 15q autism." (PMID 29693004, 2018).
autism (continued). "And similar to the dup15 phenotype, the mouse with two fold increase in brain Ube3a (1xTg) had a weaker autism penetrance with few of behavioral deficits." (PMID 30568575, 2018). "Chromosome 15 and UBE3A have been found to be relevant for autism, increasing interest in autism traits within AS." (PMID 29037196, 2017). "Most significantly, why does a developing neuron tolerate biallelic Ube3a expression, while having more than one functional copy in adulthood leads to an autism-like phenotype and reduced excitatory neurotransmission ?" (PMID 25894543, 2015). "In mouse models, not only are reductions in UBE3A protein expression capable of inducing neurological deficits, but duplications in UBE3A also show autism-like phenotypes, such as social and learning and memory deficits." (PMID 26441497, 2015). "Here we propose that maternal interstitial duplications of the region between BP2 and BP3 are sufficient to produce an autism phenotype due most likely to overexpression of the maternally expressed UBE3A gene on the duplicated chromosomal segment." (PMID 23495136, 2013). "The identification of UBE3A targets is the first step in unraveling the molecular etiology of AS and duplication 15q autism." (PMID 23626758, 2013). "UBE3A gene was suggested as a strong candidate for autism because of its imprinted nature and maternal dominance." (PMID 22830052, 2012). "A whole genome wide screening for copy number variation revealed UBE3A as one of the affected genomic loci in autism." (PMID 22830052, 2012). "A significant positive correlation in GABRB3 and UBE3A transcript levels was observed with increased chromosomal copies when all cases (control, autism and dup15q) were analyzed as a group." (PMID 22152151, 2011). "UBE3A transcript and protein levels were significantly higher than control and autism in dup15q, as expected, although levels were variable and lower than expected based on copy number in some samples." (PMID 22152151, 2011). "UBE3A transcript was significantly increased in dup15q samples compared to both the control group and autism (P = 0.004 and P = 0.045, respectively)." (PMID 22152151, 2011). "Here, we test the hypothesis that increased dosage of Ube3a may exert a sex-biasing influence on autism-related phenotypes of high translational relevance." (PMID 38996019, 2024). "In keeping with this, animal studies have shown that the increased Ube3a dosage reconstitutes autism-like traits in animals, an effect that may be mediated by impaired glutamatergic transmission." (PMID 38996019, 2024). "Our results uncover a powerful sex-biasing genomic influence of Ube3a that could explain some of the sex bias in autism and related neurodevelopmental disorders." (PMID 38996019, 2024). "UBE3A’s location is 15q11–13, regularly duplicated in autism cases." (PMID 39457068, 2024). "Here, we test the hypothesis that increased dosage of Ube3a may influence autism-relevant phenotypes in a sex-biased manner." (PMID 38996019, 2024). "A key mechanism that may exert such sex-differential multiomic effects in autism may reside within the function of the ubiquitin protein ligase E3A (Ube3a)." (PMID 38996019, 2024). "Interestingly, the opposite molecular condition, Dup15q, where the UBE3A gene is duplicated on the maternal chr15q11.2-q13, is also characterized by autism, intellectual disability, hypotonia, language developmental delay and language deficits, and epilepsy." (PMID 36012404, 2022). "Firstly, we searched the results of genome-wide association analysis (GWAS) for autism in the Psychiatric Genomics Consortium database, no positive sites for UBE3A gene were found to be associated with autism at the genome-wide level." (PMID 33308194, 2020). "Moreover, even PWS and AS specific genes that lie in the BP2-BP3 PWS/AS region, such as, MAGEL2, SNRPN, UBE3A, and ATP10A are also significantly co-associated with autism (Malacards.org; SFARI.org)." (PMID 32384786, 2020).
autism (continued). "Interestingly it has been reported that in neurons of the UBE3A-autism mouse model, the overexpression of UBE3A induces the cleavage of MTs, thus leading to local degeneration and retraction of dendritic branches." (PMID 31798818, 2019). "UBE3A lies in the chromosomal region 15q11-13, which is commonly duplicated in autism." (PMID 31481879, 2019). "Other genes coding for GABAA (γ-aminobutyric acid type A) receptor subunits β3, α5, γ3, and CYFIPI (cytoplasmic FMRP-interacting protein 1) are also reported in autism, which suggests the involvement of genes other than UBE3A lying within the 15q11–q13 region in autistic pathophysiology." (PMID 30568575, 2018). "Unique patterns of UBE3A expression within the cerebral cortex could have important functional implications, especially given the cognitive manifestations of both AS and autism." (PMID 30364390, 2018). "Further, linkage disequilibrium at the 5′ end of UBE3A in families of autistic children and paternally derived mutations at the same site not resulting in an autistic phenotype makes UBE3A a candidate gene for susceptibility to autism and related disorders." (PMID 30568575, 2018). "Several candidate autism susceptibility genes were hypermethylated (P <0.05) in the HMFA, including Shank3, Cacana1g, Gtf2i, Rapgef4, and Nbea in male offspring and Ext1, Ube3a, Erbb4, Grip1, Grm8, Reeln, Shank3, and Rbfox1 in female offspring." (PMID 24484737, 2014). "Expression of UBE3A gene was reduced in Angelman, Rett and autism post mortem brain samples." (PMID 25226172, 2014). "These abnormal monoamine levels could be responsible for many of the behavioral abnormalities observed in both AS and autism, but further investigation is required to determine if any of these changes are purely dependent on Ube3a levels in the brain." (PMID 22916201, 2012). "Interestingly, mice over expressing triple the dose of UBE3A showed autism traits like impaired communication, defective social interaction, and increased repetitive stereotypic behavior." (PMID 22830052, 2012). "Glutamatergic synaptic defects observed in a recent mouse model for autism due to increased Ube3a alone do not entirely reflect the inverse effects of lower levels observed in Ube3a deficient animals." (PMID 22916201, 2012). "In addition, the variability in UBE3A transcript levels between individual dup15q samples was significantly greater than in control or idiopathic autism samples (P = 0.002 and P = 0.045, respectively; Levene's test for equality of variances)." (PMID 22152151, 2011). "Through these functions, Ube3a can thus affect the transcriptomic and proteomic architecture of the developing brain and may serve as a putative effector of sex-specific phenotypes of relevance to autism." (PMID 38996019, 2024). "The favored strategy has not been the ectopic expression of UBE3A, amid fears of elevating the dosage of UBE3A, a known cause of the autism and epilepsy-related Dup15q syndrome, but rather the reactivation of the intact, albeit silenced paternal copy of the UBE3A gene." (PMID 37928900, 2023). "Notably, both studies also reported symptoms of autism, which suggests that overexpression of UBE3A might also contribute to the increased prevalence of autistic characteristics in patients with an mUPD." (PMID 35887798, 2022). "Some studies have indicated that the maternally expressed UBE3A gene may be a major contributor to the autism phenotype in these individuals since in both interstitial and isodicentric duplications, there is a clear bias towards maternally derived or inherited duplications where ASD is present." (PMID 29423132, 2018). "Likewise, a mouse model with increased gene dosage of Ube3a demonstrates autism-like behaviors." (PMID 25894543, 2015).
autism (continued). "Using ubiquitous overexpression of FLAG-Ube3a in a BAC transgenic mouse model for autism, we found that the circadian period of the SCN in vitro was shortened by the enhanced expression of Ube3a compared with that in WT SCN from the same mixed background." (PMID 35401134, 2022). "Previously developed genetic autism mouse models (SETD5, UBE3A, SHANK3, Timothy syndrome) also observed reduced neurite outgrowth, sometimes in concert with the reduced synaptic connectivity." (PMID 33727673, 2021). "Cases I and II, are carriers of the same duplication on chromosome 15 [15q11.2q13.1(SNRPN,UBE3A,ATP10A,GABRB3,OCA2) x3], both have severe autism but with different levels of cognition." (PMID 28174603, 2017). "Perhaps the most relevant connection between autism and UBE3A expression levels may be that increased activity of this Na+/K+ pump has been detected in the frontal cortex and cerebellum of individuals with idiopathic autism as compared to typically developing individuals." (PMID 23626758, 2013). "Additionally, experiments administering topoisomerase inhibitors to cerebral organoids have revealed reduced expression of UBE3A-ATS, indicating potential implications for autism spectrum pathology." (PMID 40255860, 2025). "Understanding the complex interactions between PKA and Ube3a in the regulation of SK2 synaptic levels might provide new platforms for developing treatments for AS and various forms of autism." (PMID 32555345, 2020). "MYT1L is not the only autism related gene to show differential sex effects, so similar experiments should be done in other models (Shank3, Ube3a) to determine how generalizable these gonadal and chromosomal contributions are to neurodevelopmental traits, and with updated FCG mice." (PMID 39966983, 2025). "However, it is currently not clear whether an increase in UBE3A dosage alone accounts for the autism phenotypes." (PMID 26491538, 2014). "Both UBE3A and SNORD116 mRNA levels were positively correlated with all developmental functioning scores in the deletion AS group (p < 0.001), and autism features (p < 0.001) in the non-deletion PWS group." (PMID 33116122, 2020). "In contrast to both UBE3A and GABRB3, SNRPN levels were significantly negatively correlated with percentage PWS-IC methylation in all cases but not with dup15q, control or autism cases analyzed separately." (PMID 22152151, 2011).
cervical carcinoma (47 papers, 2004 to 2026). A carcinoma arising from either the exocervical squamous epithelium or the endocervical glandular epithelium. "The involvement of UBE3A (also known as E6AP) in viral oncogenesis was first established in HPV-associated cervical cancer." (PMID 33670160, 2021). "Hijacking of ubiquitin E3 ligase E6AP/UBE3A by high risk human papilloma virus E6 oncoprotein contributes to cervical cancer by inducing ubiquitination and in turn degradation of tumor suppressor p5335–37." (PMID 32157086, 2020). "In addition to UBE3A roles in neurodevelopment, alterations in UBE3A levels were associated with cancers such as cervical cancer, prostate cancer, and breast cancer." (PMID 32532103, 2020). "We have demonstrated that UBE3A not only degraded ANXA1 in cervical carcinoma cell lines but was also involved in determining the stability of ANXA1 in renal cancer cells." (PMID 34319001, 2021). "In this study, we show that HPV-positive cervical cancer lines contain low levels of DINO as a consequence of HPV16 E6/UBE3A-mediated degradation." (PMID 32546626, 2020). "UBE3A was originally named E6-associated protein (E6-AP) since the protein interacts with the E6 protein expressed by infected human papillomavirus (HPV), which causes cervical cancer, other anogenital cancers, and oropharyngeal cancers." (PMID 37541588, 2023). "However, the relevance of this function for the development of AS or cervical cancer is unclear (e.g. this property is not affected in E6-AP mutants derived from AS patients with point mutations in the UBE3A gene)." (PMID 18047743, 2007). "MiR-375 was found to be the target of Ubiquitin-protein ligase E3A (UBE3A) in cervical cancer, and the improvement of radio sensitivity in HR-HPV (+) cervical cancer is highly correlated with miR-375-UBE3A axis." (PMID 30379973, 2018).